AR (androgen receptor)
Diseases named in the same sentence as AR in open-access papers (continued):
Sharing a sentence is not in itself a finding about the gene and the disease.
prostate carcinoma (continued). "AR remains functional and expressed in nearly all primary prostate cancers." (PMID 28570625, 2017). "These experimental results validate the prediction that phenothiazine inhibits signal transduction through the androgen receptor and may, therefore, be useful for the treatment of prostate cancer." (PMID 28071740, 2017). "Further studies are warranted to test this hypothesis and determine the relationship between AR and ERβ2 in the presence of 27-OHC in the context of wildtype AR + prostate cancers." (PMID 28503095, 2017). "Indeed, both pathways have been reported to be involved in AR regulation and established pathways that promote human prostate cancer." (PMID 28157714, 2017). "The development of true androgen independence in prostate cancer may well be via oncogenic activation of the intracellular pathways that lead to replication licensing, bypassing AR." (PMID 28504694, 2017). "AR-FL plays a critical role not only in normal prostate but also in prostate cancer." (PMID 29181019, 2017). "Downregulation of androgen receptor and 5α-reductase 2, along with upregulation of 5α-reductase 1 in tumors may promote prostatic intraepithelial neoplasia and prostate cancer development in TRAMP mice." (PMID 28493878, 2017). "Accordingly, DDB2 expression may be induced in prostate cancer tissues with high levels of AR expression." (PMID 28212551, 2017). "In support of this concept, 2A-DUB/MYSM1 was originally discovered as regulator of androgen receptor-dependent gene expression in a co-regulatory complex with histone acetylase p/CAF in prostate cancer cells that displayed reduced overall levels of H2A-K119ubi compared with normal prostate tissue." (PMID 28978033, 2017). "Here, our analysis confirmed the positive epidemiological association between prostate cancer and MPB at Xq12 (AR/EDA2R-locus), pointing towards a shared pathophysiological mechanism that may involve EDA2R-signalling and AR-transactivation." (PMID 28272467, 2017). "PPARs, in particular PPARγ, is deregulated in prostate cancer, and PPARγ may also regulate AR activity." (PMID 28099154, 2017). "Also consistent with bone marrow-derived MSCs, inhibition of TGF-β activity enhances adipogenesis in prostate cancer-derived MSCs with AR inhibition having a small additive effect in this context." (PMID 28493842, 2017). "In this report, we showed that RSV is capable of inhibiting ARV7-mediated transcription of AR target genes in prostate cancer cells by downregulating the protein levels of both ectopically and endogenously expressed ARV7 without affecting either mRNA levels nor its nuclear translocation." (PMID 28903374, 2017). "Most of those genes have been reported to be involved in AR signaling and cancer prostate cancer." (PMID 28262798, 2017). "Additionally, reporter assays revealed that canine REIC/Dkk-3 restored AR signalling in both human and canine androgen-independent prostate cancer cells." (PMID 28599655, 2017). "MAZ also has a role in prostate cancer by interacting with the androgen receptor." (PMID 29119102, 2017). "AR signaling is essential for the progression of prostate cancer." (PMID 28671964, 2017). "We applied HOCUS to TCGA prostate adenocarcinoma (PRAD) copy number data because prostate cancers are known to harbor significant copy number events over the evolution of the tumor including AR amplifications, TMPRSS2-ERG fusions, and even whole genome level events such as chromoplexy." (PMID 28359308, 2017). "The mechanism for the switch from homeostatic to proliferative AR signaling in prostate cancer is unknown." (PMID 28420128, 2017). "Identification of AR pathway suppression by miR-24 may explain why AfA prostate cancer patients had higher PSA levels." (PMID 28157714, 2017). "Multiple forms of AR also promote the growth of both early and late stage prostate cancers." (PMID 29181019, 2017).
prostate carcinoma (continued). "Moreover, CCND1 is known to further negatively regulate the AR function, not only by directly binding to AR to inhibit transactivation of AR, but also by attenuating AR-induced upregulation of Klk4 in prostate cancer." (PMID 29249975, 2017). "Collective observations based on our studies led us to hypothesize that ID4 could be involved in selectively regulating AR activity through FKBP52 in prostate cancer." (PMID 28252832, 2017). "Therefore, identification of AR downstream signals and new molecular mechanisms for AR activation are important to improve the treatment of advanced prostate cancer." (PMID 28783103, 2017). "Accordingly, as compared with abiraterone and orteronel, enzalutamide may have more selective effects on the AR signaling pathway in prostate cancer cells." (PMID 28938672, 2017). "In addition, we showed that canine SGTA played an inhibitory role in AR signalling both in canine and human androgen-independent prostate cancer cells." (PMID 28599655, 2017). "Additionally, AR-targeted therapies have also had great success; the small molecule Sigma1 inhibitor suppresses AR function and further suppresses prostate cancer in vivo and in vitro." (PMID 29149895, 2017). "Here, we will compare how the AR and GR interact with DNA and chromatin; how they evoke tissue-specific transcriptional responses and in how far they have interchangeable functions, for instance, in prostate cancer." (PMID 28168446, 2017). "Therefore, the ability of AA to suppress AR and decrease PC-3 proliferation can be potentially employed in the prostate cancer chemoprevention and chemotherapy." (PMID 28286531, 2017). "Thus, we can expect that inhibition of these miRNAs directly targeting AR expression is an important pathway for development and progression of prostate cancer." (PMID 28783103, 2017). "Androgen receptor is a well known therapy target in prostate cancer treatment." (PMID 29108248, 2017). "Androgen receptor (AR) signaling remains the major oncogenic pathway in prostate cancer (PCa)." (PMID 28275218, 2017). "In support of its use as a negative prognostic marker in prostate cancer an investigation of 115 hormone naïve radical prostatectomy specimens demonstrated that higher tumour AR gene expression was associated with shorter time to biochemical recurrence." (PMID 27902483, 2017). "Furthermore, the renewed expression of serum PSA levels and AR expression in castrate-resistant disease is evidence that, even in advanced disease, prostate cancer cells remain almost exclusively dependent on the AR." (PMID 27902483, 2017). "Androgen receptor (AR) plays a critical role in prostate cancer (PCa) development and progression." (PMID 29285272, 2017). "In addition, cultured mast cells downregulated mRNA levels of androgen receptor of human prostate cancer cell lines, leading to increased invasiveness and migration ability of cancer cells." (PMID 29379802, 2017). "AR also functions as a regulator of metabolism within human prostate cancer cells." (PMID 29181019, 2017). "Reports from different groups showed that prostate cancer cells expressing constitutively active AR splicing variants respond to neither of these reagents." (PMID 28903374, 2017). "While these reports confirm dynamic interactions between TSG101 and AR, the role of TSG101 in AR signalling may be temporal in prostate cancer." (PMID 28881726, 2017). "In prostate cancer, CTC counts have been associated with prognosis and importantly, isolated CTCs can function as a surrogate tumour samples to detect therapy-determining biomarkers, including the mRNA based androgen receptor variant AR-V7 in CTCs." (PMID 28498319, 2017).
prostate carcinoma (continued). "The expression of “WWC1” is influenced by AR signaling and is increased in prostate cancer." (PMID 28148240, 2017). "Geneistein modulates expression of AR and its transcriptional activity in prostate cancer." (PMID 29295509, 2017). "Adding complexity to early trials is the issue of interpreting a rising PSA, the most commonly measured marker of response in prostate cancer, in the context of potential activation of AR transcription with resultant PSA rises following PI3K pathway inhibition." (PMID 28420128, 2017). "Hence, there is a need to focus on new agents that are responsible for inhibition of AR-dependent and -independent progression of prostate cancer." (PMID 29215592, 2017). "Additionally, androgen stimulates the activity and production of FGF2 and FGF-binding protein in PC3 prostate cancer cells with stably overexpressed AR." (PMID 28077787, 2017). "Taxanes antagonize the androgen receptor signaling pathway in prostate cancer cells by blocking dynein-mediated protein trafficking along interphase microtubules, and paclitaxel decreases the endocytic trafficking of epidermal growth factor receptor in lung cancer cells." (PMID 29246518, 2017). "Anyway, the association between ETV5 or SOX9 expression level and the presence of AR variants in prostate cancer cells is not clear." (PMID 29069764, 2017). "The prostate cancer cell line C4-2 expressing AR was used as positive control." (PMID 29030639, 2017). "So we speculate whether AR can regulate the growth of neuroblastoma as it functions in prostate cancer cells." (PMID 28326012, 2017). "Effective targeting of AF-2 of AR presents a new direction for anti-AR drug design that could be integrated in traditional prostate cancer treatment regimens." (PMID 29050220, 2017). "This ability to determine key resistance-mediating AR modifications facilitates a personalized approach for decision-making in therapeutic sequences and may considerably improve prolonged prostate cancer treatment and patient survival." (PMID 28380417, 2017). "The role of AR is widely studied and recognized in prostate cancer." (PMID 28423563, 2017). "Here, we provide the first comprehensive study characterising the global dynamics and function of H2A.Zac at enhancers in prostate cancer and demonstrate that H2A.Zac plays an active role in AR-enhancer function during androgen treatment suggesting an pro-oncogenic role in cancer." (PMID 29116202, 2017). "We find that ING3 levels and AR activity positively correlate in prostate cancer." (PMID 28511652, 2017). "Prostatic stromal AR abundance is also important in prostate cancer progression." (PMID 29145476, 2017). "Our findings also suggest that GPRC6A, by mediating the non-genomic effects of testosterone, may provide alternative pathways to androgen receptor signaling in prostate cancer." (PMID 28659174, 2017). "Supporting the importance of AR to prostate cancer biology is the observation that AR target genes (e.g., PSA) are usually expressed even in men progressing on androgen deprivation therapy (ADT), with AR pathway alterations commonly observed in late stage disease." (PMID 28085048, 2017). "Furthermore, it is revealed that endothelial cells within the prostate cancer microenvironment secreted IL-6, resulting in the downregulation of androgen receptor (AR) signaling in prostate cancer cells, which enhance the invasion of cancer cells." (PMID 29197379, 2017). "However, RNF6 was found to mediate an atypical ubiquitination of the androgen receptor (AR) and promotes the transcriptional activity and specificity of AR in prostate cancer." (PMID 28223545, 2017). "Since it has been reported that the transcriptional activity of ARV7 is partially dependent on the expression of full-length AR, we wanted to determine if ARV7 is capable of regulating AR target gene expression in a full-length AR-free prostate cancer cellular environment." (PMID 28903374, 2017).
prostate carcinoma (continued). "Inhibition of USP14 may be a highly effective therapy for prostate cancer through degrading AR protein." (PMID 29039082, 2017). "Previously, we showed that PHB-repressed AR activity and androgen-stimulated growth of LNCaP prostate cancer cells and that RNA interference-mediated knockdown had the opposite effects, and sensitised cells to low levels of androgens, both in vitro and in vivo." (PMID 28504694, 2017). "As seen in prostate cancer cells, androgens could induce AR expression and its nuclear translocation as well as ARE promoter activity in bladder cancer cells." (PMID 28241422, 2017). "Proliferation of prostate cancer cells is known to depend on androgen receptor (AR) signaling." (PMID 28338058, 2017). "Our recent study revealed that the overexpression of REIC/Dkk-3 in the human androgen-independent prostate cancer cell line PC3 upregulates AR signalling and restores the expression of prostate specific antigen (PSA) by interfering with the dimerization of SGTA." (PMID 28599655, 2017). "Furthermore, changes in key cell cycle regulators induced by the manipulation of USP14 function also support the notion that AR is a key target for USP14 in the prostate cancer cells." (PMID 28151478, 2017). "AR antagonists and compounds that indirectly reduce AR function by altering the level of circulating androgens are routinely used to treat early and late stage prostate cancer as well as a second prostatic disease, benign prostatic hyperplasia." (PMID 29181019, 2017). "Besides prostate cancer, AR expression has been described in a wide range of solid tumors including sarcomas, melanomas and carcinomas." (PMID 29108248, 2017). "A study demonstrated that men with hereditary prostate cancer who followed radical prostatectomy had a higher percentage of cells expressing AR and lower percentage of cells expressing the alpha-receptor for oestrogen, compared to men with sporadic prostate cancer." (PMID 28255369, 2017). "AR plays an important role in the development and progression of prostate cancer." (PMID 28570625, 2017). "It has indicated that the overexpressed PCA3 could modulate prostate cancer cells survival by altering androgen receptor (AR) signaling." (PMID 28915709, 2017). "The AR transcriptionally controls in the order of 700 genes within prostate cancer cells." (PMID 28382513, 2017). "In addition, we demonstrated that the overexpression of the canine REIC/Dkk-3 protein upregulates AR signal transduction in both canine and human androgen-independent prostate cancer cell lines." (PMID 28599655, 2017). "While AR signaling remains the primary factor driving prostate cancer, even in the progression to CRPC44, our results demonstrate that expression of CXCR7 is essential for prostate cancer cell survival and a critical factor during the transition to castration resistance." (PMID 28596572, 2017). "AR antagonists are known to inhibit the growth of androgen dependent prostate cancer cells." (PMID 28099154, 2017). "Pyrvinium inhibits AR dependent gene expression and prostate cancer cell growth, which may result from its inhibitory effect on Wnt signaling through potentiating casein kinase 1α (CK1α) kinase activity." (PMID 28400729, 2017). "Unlike in prostate cancer, focal amplification or protein-altering somatic mutations of AR have not been found in SDC or ACC." (PMID 28208703, 2017). "Indeed, there is a strong correlation between the occurrence of prostate cancer and the expression of ER stress protein markers, mainly via AR signal transduction." (PMID 28338058, 2017). "Current results suggest that there are separate basal and luminal prostate SC populations, and support the idea that stem-like AR-expressing luminal cells could function as cancer-initiating and relapse-initiating cells in prostate cancer." (PMID 28446230, 2017). "Androgen receptor plays an important role in the occurrence and development of prostate cancer." (PMID 28245841, 2017).
prostate carcinoma (continued). "Interestingly, the expression of HOXB13 was also found as an independent prognostic marker in primary prostate cancer and to correlate with AR expression." (PMID 28555048, 2017). "Importantly, FOXA1 and POU2F1 (also known as OCT1) are also known to cooperate with GATA2 and AR in the expression of androgen-regulated genes and FOXA1 is frequently mutated in advanced prostate cancer patients." (PMID 28038451, 2017). "Because the activity of some of these genes is correlated with oncogenic processes, this supports the hypothesis that re-expression of GR in castration-resistant prostate cancer could explain the progression into an AR-independent form of the disease." (PMID 28168446, 2017). "However, recent data from our laboratory suggest that AR activation can suppress PPARγ expression and/or activity within human prostate cancers." (PMID 29181019, 2017). "Thus, there is a need for the identification, characterization, and therapeutic targeting of novel molecular mechanisms and distinct regulatory proteins that promote prolonged AR activation in the advanced stages of prostate cancer." (PMID 28252832, 2017). "Our aim was to investigate whether the interaction between canine REIC/Dkk-3 and SGTA affects AR signalling and might contribute to the development of new strategies in canine androgen-independent prostate cancer treatment." (PMID 28599655, 2017). "To determine whether the efficacy of Exo2 depends on AR activity, we utilized four prostate cancer cell lines in this study." (PMID 28830537, 2017). "Unfortunately, examining H3K27ac ChIP-seq data in multiple prostate cancer cell lines suggested that AR, HOXC6 and NKX2-2 are not broadly associated with super enhancers." (PMID 28397780, 2017). "Interestingly, miR-320 mediates the effect of histone deacetylase inhibitor in prostate cancer by targeting AR expression." (PMID 28783103, 2017). "The major important target of miRNAs in prostate cancer is AR signaling." (PMID 28783103, 2017). "Moreover, co-administration of Rosa rugosa extracts and flutamide—an androgen receptor antagonist commonly used in prostate cancer chemotherapy— resulted in a higher transcription blocking." (PMID 28587101, 2017). "Indeed, it has been reported that soy isoflavones, in particular equol, suppressed AR as well as PSA expression at the transcription level in prostate cancer cells." (PMID 28239427, 2017). "According to many studies, the AR is important in prostate cancer progression." (PMID 28212551, 2017). "In summary our study demonstrates that H2A.Zac nucleosome incorporation plays a key role in facilitation of ectopic activation of AR-enhancers, which has major implications regarding the mechanism of oncogene deregulation and potential chromatin therapy options for prostate cancer." (PMID 29116202, 2017). "Importantly, AR is highly activated in prostate cancer and fuels prostate cancer by upregulating glycolysis and fatty acid metabolism." (PMID 29262542, 2017). "Hence, the potent anti-tumor effect of b-AP15 on both androgen receptor-dependent and -independent PCa cells identifies a new promising therapeutic strategy for prostate cancer." (PMID 28968984, 2017). "However, few studies have explored the significance of AR phosphorylation at this site in prostate cancer in the clinical setting." (PMID 27902483, 2017). "To test this hypothesis, we examined the relationship between IRE1α pathway signaling and CREB3L4 in AR-induced prostate cancer cell proliferation." (PMID 28338058, 2017). "Prostate cancer is driven by androgen stimulation of the androgen receptor (AR)." (PMID 28191869, 2017). "AR is a testosterone-activated transcription factor and a crucial protein in prostate cancer." (PMID 28542476, 2017). "Although upregulation of SGTA expression may not be related to hormonal signalling, overexpressed SGTA plays an important role as an inhibitor of AR signalling and confers the androgen-independent characteristics in prostate cancer." (PMID 28599655, 2017).